TLR2 (toll like receptor 2)
Diseases named in the same sentence as TLR2 in open-access papers (continued):
Sharing a sentence is not in itself a finding about the gene and the disease.
allergic asthma (24 papers, 2005 to 2025). A asthma with a basis in a pathological type I hypersensitivity reaction. "Polymorphisms in the tlr2 and tlr6 genes were found to be linked with the susceptibility to developing allergic asthma." (PMID 39273551, 2024). "However, despite more and more advances in our understanding of the role of TLR2 in allergic asthma, the mechanism underlying TLR2 regulation in allergic airway inflammation is still elusive." (PMID 32117301, 2020). "Several epidemiological analyses have highlighted positive associations between TLR2, TLR4 and CD14 (TLR4s co-receptor) gene polymorphisms and allergic asthma susceptibility in human." (PMID 24098413, 2013). "The aim of the present study was to evaluate the effect of TLR2/6 agonist administered locally by nasal instillation after the allergic airway reaction was established in a mouse model to mimic potential treatment of allergic asthma." (PMID 39273551, 2024). "In this article, we aimed to evaluate whether pulmonary administration of TLR2/6 agonist FSL-1 to mice would be able to modify airway responses in an established allergic asthma model." (PMID 39273551, 2024). "Finally it has been proposed that HDM extract can distinctly trigger allergic rhinitis through the β-glucan TLR2 dependent activation of the upper airways or allergic asthma through the LPS-induced TLR4 activation of the lower airways." (PMID 24098413, 2013). "Moreover, in line with our observation that plant sterols and stanols act via TLR2, Aumeunier and coworkers have shown in an elegant series of experiments that systemic TLR2 activation suppressed experimental allergic asthma in NOD mice." (PMID 23091602, 2012). "Additionally, TLR2/4 agonisation during allergen challenge in sensitised mice prevented allergic asthma." (PMID 18315836, 2008). "Our data show that, despite having adverse acute effects, TLR2 agonist treatment as a therapeutic intervention induces an expansion of the Treg cell population in the lungs and results in long-term protection against manifestation of allergic asthma upon subsequent allergen provocation." (PMID 23393567, 2013). "However, also the contrary effect could be observed: TLR2/1 agonisation aggravated allergic asthma when administered during the initial phase of the immune reaction." (PMID 18315836, 2008). "In contrast, in an allergic asthma model using the three different allergens HDM, OVA and Alternaria alternata, increased TLR2 and thymic stromal lymphopoietin (TSLP) levels in the lungs of challenged mice were found." (PMID 37426425, 2023). "It’s suggested that TLR2 agonist and miR146a mimics can protect against OVA-induced allergic asthma efficiently." (PMID 32600285, 2020). "These relations are substantiated by studies in animal model showing that TLR2 and TLR4 microbial ligands LPS or LTA modulate experimental allergic asthma." (PMID 24098413, 2013). "In this regard, it is interesting to note that bacterial TLR2 and TLR4 ligands like lipopeptides or LPS have been shown to modulate the immune response in animal models of allergic asthma." (PMID 16316467, 2005). "Moreover, several studies revealed that there are positive correlations of TLR2 and TLR4 with allergic asthma." (PMID 36012669, 2022). "To explore how TLR2 agonist and miR146a-mimic attenuate OVA-induced allergic asthma, we considered Th1 cytokines, including IgE, IL-4, IL-5 and IL-13, might be involved." (PMID 32600285, 2020). "Inspired by the findings in previous studies, we propose that a combination of TLR2 agonists and miR-146a mimics may have a better response to OVA-induced allergic asthma." (PMID 32600285, 2020). "Our findings reveal a pro‐inflammatory role of airway ECs through a TLR2‐dependent TSLP production, which may have implication for treating allergic asthma." (PMID 30184256, 2018). "A haplotype involving TLR +596 C and TLR2 +1349 C was also not related to allergic asthma in Norwegian asthmatic children." (PMID 27495363, 2016).
allergic asthma (continued). "We tested the effect of agonists of TLR2 (P40 protein of Klebsiella pneumoniae and the Pam3Cys lipopeptide), TLR3 (double-stranded RNAs Poly(I∶C)), TLR4 (LPS and lipid A) and TLR7 (R848) on experimental allergic asthma and autoimmune diabetes in the NOD mouse." (PMID 20628601, 2010). "Thus, we concluded that MUC5AC expression is regulated by sNASP/TRAF6 signaling via TLR2 and TLR4, which may provide a novel therapeutic strategy for allergic asthma." (PMID 36012669, 2022).
HIV-1 infection (24 papers, 2009 to 2025). The type species of lentivirus and the etiologic agent of acquired immunodeficiency syndrome (AIDS). "Specifically, we recently showed that chronic untreated HIV-1 infection was associated with aberrant expression and responsiveness of TLR2, 3, 4, 6, 7/8 in PBMCs _." (PMID 23300756, 2012). "Thus, the presence of SNP rs111200466 (−196 to −174 Ins/Del) in the TLR2 gene is a risk factor for HIV-1 infection and disease progression." (PMID 41305532, 2025). "The observed difference in TLR2 expression in infected PBMCs from different female donors once again indicates that the genetics of the host play an important role in the susceptibility of cells to HIV-1 infection." (PMID 37513727, 2023). "Experiments using tissue explants have shown that gram-positive bacteria such as Staphylococcus aureus, Group B Streptococcus and genital pathogens such as Candida albicans and Neisseria gonorrhea increase Langerhans' cells susceptibility to HIV-1 infection via TLR2 agonists and TNF-α production." (PMID 20066050, 2010). "Another study reported that soluble TLR2 played a significant role in inhibiting cell-free HIV-1 infection, HIV-induced NF-κB activation, and inflammation in infants breastfeeding from their HIV-infected mother." (PMID 37298575, 2023). "We further reported a significant increase in TLR2 expression in BM cells, and that the overexpression of TLR2 in reporter cells greatly enhanced HIV-1 infection in vitro." (PMID 30930906, 2019). "We initially attempted to identify and screen TLRs present in human BM and previously reported that soluble TLR2 (sTLR2) is present in human BM and significantly inhibits HIV-1 infection." (PMID 30930906, 2019). "The significance of the TLR2 and TLR6 TMDs in the regulation and activation of formation of the receptor complex and in downstream signaling has been recently described, revealing that activation of TLR2 increases resistance of macrophages to HIV-1 infection." (PMID 25121610, 2014). "Although experiments with Jurkat T cells transfected with TLR2 demonstrate that PIM6 effect on HIV-1 infection of T cells depends at least in part on this receptor, co-engagement of a second receptor cannot be ruled out." (PMID 24282561, 2013). "Activation of TLR2+ JLTRg-R5 T cells (JLTRg-R5-TLR1-TLR2) in the presence of PIM6 resulted in increased HIV-1 infection as measured by intracellular p24 expression compared to cells activated in medium alone." (PMID 24282561, 2013). "A TLR2-mediated enhancement of virus replication was seen only when stimulation took place before HIV-1 infection, thus suggesting that the signalling cascade triggered by the agonist acts most likely at an early step in the virus life cycle." (PMID 19419540, 2009). "It has been recently reported that productive HIV-1 infection of immature monocyte-derived DCs is enhanced following TLR2 engagement by Neisseria gonorrhoeae." (PMID 19419540, 2009). "The possibility that TLR2 triggering is positively affecting the early steps of HIV-1 infection in IM-MDDCs is confirmed by quantitative measurements of reverse transcripts and integrated viral DNA copies." (PMID 19419540, 2009). "The role of TLR2 in regulating HIV-1 infection in vivo has yet to be well described." (PMID 38140264, 2023). "The precise involvement of TLR2 in regulating HIV-1 infection in vivo remains an enigma." (PMID 38140264, 2023). "Gonococci activate dendritic cells through TLR2, enhancing HIV-1 infection of these cells." (PMID 35223556, 2022). "TLR2 agonist enables IFN-I production upon HIV-1 infection of THP-1 cells." (PMID 34844429, 2021). "Whether TLR2 and TLR10 interact and associate with each other in the context of an HIV-1 infection remains unclear and will be intriguing to investigate in future studies." (PMID 30930906, 2019).
HIV-1 infection (continued). "Furthermore, we were the first to demonstrate that soluble TLR2 (sTLR2), which is highly prevalent in human breast milk (BM) serves as an innate antiviral factor in BM and significantly inhibits HIV-1 infection and integration in vitro." (PMID 30930906, 2019). "Interestingly, HIV-1 infection of monocyte-derived macrophages and peripheral blood mononuclear cells has been observed to up-regulate TLR-2 and TLR-4 expression." (PMID 28949981, 2017). "Furthermore, morphine exposure has also been shown to modulate the expression of microglial TLRs (TLR2/4), thereby contributing to accelerated neuropathogenesis in a model of human immunodeficiency virus (HIV)-1 infection." (PMID 26860188, 2016). "It has been shown that Mtb can promote HIV-1 infection by increasing the expression of CXCR4 and CCR5, the two HIV-1 co-receptors and increase the susceptibility of CD4+ T cells to HIV-1 infection through a TLR2-mediated pathway." (PMID 27004401, 2016). "Conversely, the extracellular portion of TLR2, which is found systemically and in mucosal fluids, significantly inhibits pro-inflammatory cytokine production and directly inhibits cell-free HIV-1 infection in vitro." (PMID 26347747, 2015). "Moreover, we demonstrated that cellular TLR2 expression significantly increased HIV-1 infection/integration in vitro." (PMID 26347747, 2015). "Thus, some translocated microbial products can directly induce B cells to differentiate into IL-10-producing B cells in untreated HIV-1 infection via TLR-2 and/or TLR-9 signaling pathway." (PMID 24586620, 2014). "In addition, others have demonstrated that TLR2 engagement enhances HIV-1 infection in primary CD4+ T cells." (PMID 24282561, 2013). "Given the large quantity of sTLR2 in BM observed in our laboratory as well as others, and the role of TLR2 in sensing and activating anti-viral responses to a number of viruses, we hypothesized that BM sTLR2 may play a role in inhibiting HIV-1 infection." (PMID 22792230, 2012). "In addition, TLR2 signaling has been shown to activate T cells to be more susceptible to productive infection with HIV-1 and TLR2 agonists may increase the susceptibility to HIV transmission to T cells by DCs, a target for HIV-1 infection in genital tissues." (PMID 23435233, 2013). "For this purpose, HIV-1 reporter TZMbl cells were transiently transfected alone or in combination with plasmids overexpressing TLR10 and the heterodimers, TLR2 and TLR1, followed by HIV-1 infection and measurement of luciferase activity." (PMID 30930906, 2019). "The results showed a significantly increased rate of HIV-1 infection in TZMbl cells overexpressing TLR10 and heterodimers TLR1 or TLR2 compared to the empty vector alone, uninfected control or a T20 control (Enfuvirtide; HIV-1 fusion inhibitor) (P < 0.05)." (PMID 30930906, 2019). "Recently we demonstrated that soluble TLR2 (sTLR2) physically inhibited HIV-induced NFκB activation and inflammation, as well as HIV-1 infection." (PMID 26347747, 2015). "We chose to study TLR2 and TLR9 because of the important role they play in HIV-1 infection." (PMID 37513727, 2023). "In addition, HIV-1 infection was significantly elevated in TZMbl cells, which were either co-transfected with TLR1/10 or TLR2/10 compared to the control (P < 0.05)." (PMID 30930906, 2019). "Next, we determined the extent of HIV-1 infection in TLR10 and TLR2 stable reporter cell lines." (PMID 30930906, 2019). "Given that TLR10 is a homolog of both TLR2 and TLR1, we hypothesized that TLR10 is involved in sensing specific HIV-1 structural proteins, which leads to increased cellular activation and HIV-1 infection." (PMID 30930906, 2019). "Taken together these data indicated that cellular expression of TLR2 played an important role in significantly increased HIV-1 infection compared to cells that did not express TLR2, and TLR2 effects were blocked by anti-TLR2 Ab." (PMID 26347747, 2015).
HIV-1 infection (continued). "In spite of their structural relatedness, our results indicate that PIM6 is unique among mycobacterial mannosylated glycolipids in its ability to increase HIV-1 infection in primary CD4+ T cells and this is at least partially related to its ability to engage and signal via TLR2." (PMID 24282561, 2013). "Importantly, TLR2-specific polyclonal and monoclonal antibody addition to BM prior to cell-free R5 HIV-1 addition led to significantly (P<0.01, P<0.001, respectively) increased HIV-1 infection in TZM-bl reporter cells." (PMID 22792230, 2012). "Surprisingly, with the exception of TLR1 and TLR2, we found significantly higher levels of TLR10 (>100-fold) expression in BM samples collected from HIV-1 infected Nigerian women, thus indicating that TLR10 might play an important role in HIV-1 infection and pathogenesis." (PMID 30930906, 2019). "Therefore, it is highly likely that TLR2 and TLR10 are independently involved in the regulation of HIV-1 infection in a non-heterodimeric form." (PMID 30930906, 2019). "The reason why LM being a strong TLR2 agonist in the HEK293 assay, does not co-stimulate or significantly increase HIV-1 infection in primary CD4+ T cells may be related to a dominant TCR inhibitory effect of this glycolipid." (PMID 24282561, 2013). "Moreover, based on TLR10 and TLR2 co-transfection or co-depletion through siRNA and effect on HIV-1 infection or integration, TLR10 appears to play a role in HIV-1 infection and integration independent of TLR2 since no additive effect of TLR10 and TLR2 was observed." (PMID 30930906, 2019).
osteoarthritis (24 papers, 2010 to 2025). A noninflammatory degenerative joint disease occurring chiefly in older persons, characterized by degeneration of the articular cartilage, hypertrophy of bone at the margins and changes in the synovial membrane. "Among the downregulated exosomal miRNAs derived from SERPINE1-silenced GC cells, miR-365a-5p has been reported to promote macrophage M2 polarization by inhibiting the TLR2/MyD88/NF-κB signaling pathway in osteoarthritis." (PMID 39748408, 2025). "On the other hand, it has been shown that CD44 plays a role in stimulating TLR2 downstream targets with a subsequent progression of osteoarthritis as evidenced by the upregulation of NFκB-, IL-1B- as well as TNFA gene expression in human macrophages." (PMID 37234812, 2023). "One report by Qadri and colleagues has highlighted a role of CD44 as a regulator of TLR2 signaling in macrophages in the context of osteoarthritis." (PMID 35992852, 2022). "Fibronectin fragments (FN-fs), which are abundant in the synovial fluid of patients with osteoarthritis (OA), induce expression of matrix metalloproteinases (MMPs) via the toll-like receptor-2 (TLR-2) signaling pathway." (PMID 33903620, 2021). "Our previous studies involving patients with osteoarthritis show altered TNF-α production in response to TLR2 stimulation and elevated TLR2 and RANKL expression on blood neutrophils." (PMID 24757287, 2014). "Celastrol improves osteoarthritis by controlling the TLR2/NF-κB signaling pathway." (PMID 40391077, 2025). "Continuing research on TLR2 and ITGα5 as therapeutic targets may aid in designing novel medications for osteoarthritis." (PMID 32371954, 2020). "Our data suggested that blocking TLR2 or ITGα5 might be promising therapeutic strategy for treating progressive osteoarthritis." (PMID 32371954, 2020). "Likewise upregulation of ANK2, in both the groups was predicted to inhibit MYBBP1, which was leading to development of osteoarthritis by NF-κB activation through activation of IL-1β similar to activation of TLR2 by upregulated fibronectin." (PMID 29731966, 2018). "Expression levels of TLR2 were found increased in CD14+ CD16+ blood monocytes isolated from RA patients compared to healthy controls and such abundant expression of TLR2 was also detected in the synovial tissue of RA patients compared to patients with osteoarthritis." (PMID 26759164, 2016). "Expression of TLR2 and TLR4 has been shown to be increased in the synovial tissue of RA patients compared with healthy donors or osteoarthritis samples." (PMID 20419126, 2010). "Previously, melatonin has been reported in the treatment of osteoarthritis, but it has not been found that melatonin can treat osteoarthritis through the TLR2/4 pathway, although some studies have proposed the role of melatonin in regulating the TLR pathway in other chronic inflammatory diseases." (PMID 37240086, 2023).